TIMP1 (TIMP metallopeptidase inhibitor 1)
Diseases named in the same sentence as TIMP1 in open-access papers (continued):
Sharing a sentence is not in itself a finding about the gene and the disease.
cancer (continued). "Besides, the metastasis of cancer cells is also negatively affected by curcumin in promoting DOX efficacy via MMP-2 downregulation and TIMP-1 upregulation." (PMID 33187385, 2020). "Six were common for cancer stage (Up: GDF15, TIMP1, IL1RL1; Down: CCL22, APP, CLEC1B)." (PMID 33334063, 2020). "The profibrotic tissue inhibitor of metalloproteinases 1 (TIMP-1) is an endogenous inhibitor of various matrix metalloproteinases (MMPs), which are involved in the degradation and turnover of the ECM in fibrosis but also in cancer growth and metastasis." (PMID 32899119, 2020). "Compared with the constant and opposing patterns of TIMP-1 and TIMP-3, variable trends have been reported for TIMP-2 and TIMP-4 in human cancer, which could due to the heterogeneity of the types and stages of cancer." (PMID 33419373, 2020). "There are two key factors during the process of cancer invasion and metastasis: MMP-2 and TIMP-1." (PMID 32368309, 2020). "We evaluated the concentration of ANG-2, FGF-2, HGF, IL-8, PDGF-BB, TIMP-1, TIMP-2, TNF-α, and VEGF that are the major cytokines involved in angiogenesis in MM and other cancers and, as previously demonstrated in MM patients, directly correlate with disease activity and increase with progression." (PMID 30626425, 2019). "TIMP-1, uPA, and PAI-1 are some of the mediators of TGF-β1-induced EMT in cancer." (PMID 31200779, 2019). "TIMP-1 is a natural inhibitor of MMP9 and involves in the proliferation of cancer cells." (PMID 31372176, 2019). "Moreover, a recent study has reported that Uc.338 directly regulated the expression of TIMP-1 and promoted metastasis in colorectal metastasis, implying that a messenger RNA (mRNA)–T-UCR interaction played an essential role in the cancer." (PMID 30286729, 2018). "Moreover, Tan IIA inhibited NF-κB signalling and expression of MMP-2 and MMP-9, and increased levels of tissue inhibitor of matrix metalloproteinases type 1 and 2 (TIMP-1 and TIMP-2), therefore suppressed invasion and metastasis of cancer cells." (PMID 30373594, 2018). "In addition, IL-32γ expression with NF-κB inhibitor treatment further reduced skin inflammation, epidermal hyperplasia, and cancer cell sphere formation and downregulated expression levels of ITGAV and TIMP-1." (PMID 30486830, 2018). "TIMP1 treatment definitely mediates anti-apoptotic activity through ligand-receptor interactions via a FAK/PI3K/AKT pathway and ERK in central nervous system (CNS) injury, inflammation, and cancer cells." (PMID 29742163, 2018). "Given that TIMP1 and LCN2 may be elevated in other cancer types, they are best suited as part of a panel for subjects at increased risk such as those with a history of FPC." (PMID 30241369, 2018). "TIMP-1 overexpression has been consistently associated with cancer progress and recently reported to induce an EMT phenotype and to mediate cancer-stromal cell crosstalk, independent of its MMP-inhibitory function." (PMID 29329547, 2018). "To a lesser extent, we could note the presence of IL8, TIMP1 and MMP1 (Cancer group) that shared these characteristics." (PMID 28962550, 2017). "Although TIMP-1 has emerged as an important prognostic marker in clinical findings and a well-documented inhibitor of apoptosis in research studies, it is still unclear as to how TIMP-1 is upregulated in cancer." (PMID 26366732, 2015). "Also the areas under the curve were 0.821 for TIMP-1, 0.888 for COX-2 and 0.880 for MMP-7 statistically significant (p = 0 < 0.001) in the cancer group." (PMID 29201696, 2015). "Tissue inhibitor of metalloproteinases-1 (TIMP-1) has anti-apoptotic functions, which may protect TIMP-1 positive cancer cells from the effects of chemotherapy such as docetaxel and gemcitabine." (PMID 24884504, 2014). "We found that TIMP-1 knockdown inhibits prostate CAF proliferation and migration significantly, suggesting that TIMP-1 plays an important role in regulating CAF behaviors, which in turn modulating cancer progression." (PMID 24143225, 2013).
cancer (continued). "In cancer cells, MMP-2 and MMP-9 are controlled by their endogenous inhibitors TIMP-1 and TIMP-2." (PMID 23878609, 2013). "To reveal the cellular mechanism by which TIMP-1 promotes CAF accumulation and cancer progression in vivo, we first assessed the effects of the conditioned media (CM) derived from 22RV1-control and 22RV1-TIMP-1 cells on prostate CAF proliferation and migration." (PMID 24143225, 2013). "Tissue inhibitor of metalloproteinases-1 (TIMP-1) is one of four natural inhibitors of the matrix metalloproteinases (MMPs), the proteolytic enzymes responsible for degradation of extracellular matrix (ECM) and require for cancer dissemination." (PMID 22988515, 2012). "Although TIMP-1 was the other factor significantly elevated in CAF cells, deprivation of TIMP-1 activity did not affect cancer cell colony formation promoted by CAFs." (PMID 21249190, 2011). "A 'pure' CP sample should have minimal reactivity to TIMP1, which is secreted by luminal cells and not by cancer cells." (PMID 19737398, 2009). "It has been suggested that the stabilisation of Fas by endogenous (TIMP-1 and TIMP-3) and synthetic MMP inhibitors is responsible for increased sensitivity to apoptosis of various cell types, including Dev neural precursors cells or cancer cells." (PMID 16316466, 2005). "In addition, we found that IL-10, IL-4, and IL-6 differentially regulate TIMP-1, MMP-2, and MMP-9 mRNA and protein expression in HPV-18 immortalised human prostate cell lines derived from low and high Gleason score cancer tissue." (PMID 12771930, 2003). "pSTAT3 + reactive astrocytes hinder the access of CD8 + cytotoxic T cells to cancer cells by increasing the expression of specific immunosuppressive molecules, such as programmed cell death-1 ligand 1 (PD-L1), VEGF-A, lipocalin-2, and tissue inhibitor of metalloproteinases-1 (TIMP-1)." (PMID 39780275, 2025). "Additionally, TIMP1 regulates extracellular matrix (ECM) remodeling, which not only drives cancer progression but may also influence migrasome formation and stability by modulating ECM degradation." (PMID 40299331, 2025). "Moreover, TIMP-1 and TIMP-2, known to inhibit angiogenesis, were also present in the ADSC-EVs, which is in agreement with previous studies showing that both TIMPs were secreted via EVs (bone marrow stem cells and cancer cells)." (PMID 33916460, 2021). "In addition, all studies included in this meta-analysis used IHC but not ELISA to assess TIMP-1 expression in cancer patients." (PMID 33628641, 2021). "The pro-tumoural effects of MCP-1, proliferin, TIMP-1 and soluble ICAM-1 whilst the anti-cancer effects of IGFBP-2, endostatin and ADAMTS-1 have been published and suggest that this secretome signature may well provide a combination of effects on cancer growth." (PMID 33730293, 2021). "Fucoidan derived from U. pinnatifida sporophylls inhibit hypoxia in cancer cells through nuclear translocation, activity of HIF-1α and reduction in the levels of phosphorylated-PI3K (p-PI3K), p-Akt, p-mTOR, p-ERK, NF-κB, MMP-2, and MMP-9, but increased TIMP-1 levels." (PMID 32354032, 2020). "Although this resemblance served the purpose of properly separating cancer cell types, mesenchymal cancer cells lack expression of important tRG genes such as AQP4, FAM107A, SOX9, and GLI3, and tRG lack the expression of mesenchymal genes such as CD44 and TIMP1." (PMID 32641768, 2020). "Understanding these dynamics may have clinical implications for developing early cancer detection strategies, especially if TIMP-1 is considered a regulator of pain state and not just one involved in tissue remodeling." (PMID 31616247, 2019). "TIMP-1, TIMP-2, MMP-2 and MMP-9 are cancer metastasis related expressions, Res and PA combination could raise TIMP-1, TIMP-2 and reduce MMP-2 and MMP-9 expressions in HepG2 cancer cells, and these effects were stronger than only PA treatment." (PMID 28978315, 2017).
cancer (continued). "However, given that the FAAH substrates 2-AG and PEA likewise suppressed cancer cell invasion without (PEA) or only weakly (2-AG) increasing TIMP-1 following a 72-h incubation, additional anti-invasive mechanisms of FAAH inhibitors appear feasible." (PMID 26930716, 2016). "With respect to the cancer-specific mortality, the univariate analysis showed no significance for pT1a versus pT2a and TIMP-1 and TIMP-2 as a determinant factor, while the remaining 8 factors were significant factors of postoperative specific mortality of 247 patients." (PMID 27019657, 2016). "Up to now, the genomic contribution of TIMP-1 to cancer has not been well elucidated." (PMID 26872812, 2016). "Given that previous work from our group, as well as from other groups, had shown that TIMP-1 can be predictive of outcome in CRC, and that TIMP-1 can promote cancer cell survival through the PI3K/AKT signaling axis, we reasoned that TIMP-1 could influence response to anti-EGFR therapy." (PMID 27509063, 2016). "Thus, TIMP-1 merely functions as a biomarker for HCC progression and contributes to accelerating cancer progression, which implies that it may serve as an important HCC therapeutic target." (PMID 25909286, 2015). "Furthermore, in patients without TIMP-1 cancer cell immunoreactivity, we identified a 46% relative reduction in mortality from the addition of G to D compared to single agent D, although this difference was not statistically significant (Pinteraction = 0.06)." (PMID 24884504, 2014). "TIMP1 protein is produced by luminal cells and not cancer cells." (PMID 20021671, 2009). "The localization of TIMP‐1 may be crucial to explain its dual effects: Extracellular TIMP‐1 confined to the ECM prevents metastasis by inhibiting nearby MMPs, whereas intracellular TIMP‐1 promotes cancer cell proliferation and survival by effecting different signaling pathways." (PMID 31545548, 2019). "Finally, the TIMP-1-inducing, and therefore antiangiogenic, impact of cisplatin could not be reproduced using CM from non-cancer bronchial epithelial cells." (PMID 30344920, 2018). "As on one hand, TIMP-1 has a growth factor-like role directly affecting cancer cell growth, invasion, and migration independent of TIMP:s inhibition of MMPs, and on the other hand, both MMPs and TIMP-1 play an important role in inflammatory processes, we explored whether MMPs and CRP correlate." (PMID 29929486, 2018). "Nevertheless, evidence indicates that TIMP-1 binds to the CD63 receptor and activates noncanonical oncogenic signaling in several cancers, but its role in mediating TNBC chemoresistance is still largely unexplored." (PMID 37443843, 2023). "Interestingly, while TIMP-1 plasma levels were high, TIMP-2 amounts were low in all cancer subjects and these differences could be due to the characteristic activation mechanism of proMMP-2 and proMMP-9 that includes the participation of TIMP-2 and TIMP-1, respectively." (PMID 36213817, 2022). "Such markers should complement CEA, detecting those cancers that were not positive for CEA, with TIMP1, VEGF, sCD26 and PKM2 showing some promise." (PMID 26035703, 2015). "Negative immune-expression of TIMP1 is correlated with biochemical recurrence in patients with PC possibly by failing to control MMP-9, an important MMP related to cancer progression." (PMID 26742965, 2015). "Applying the approach of analysis TIMP-1 fucosylation in serum samples, we found that serum TIMP-1 had little or no α1, 2 fucosylation in normal and many cancer conditions." (PMID 24015777, 2013). "In the present study, we further detected the protein level of TIMPs in human LoVo cancer cells that had been exposed to PGE2, which demonstrated that PGE2 treatment shows no influence on regulating TIMP-1, TIMP-2, TIMP-3 and TIMP-4." (PMID 21859479, 2011).
cancer (continued). "While both TIMP-1 and TIMP-2 were expressed in non-neoplastic lungs (NNL) as well as in carcinomas, stromelysin 3 (ST3), 92 kDa gelatinase and interstitial collagenase were expressed only by carcinomas." (PMID 1457364, 1992). "The results indicated that SPP1, TIMP1, and SERPINE1 expression appeared to be remarkably higher in CRC tissues than in the adjacent tissues, while the expression of CXCL2 was not statistically different between cancer tissues and adjacent tissues." (PMID 32936304, 2020). "It is not yet clear whether painful and non-painful cancers differentially express TIMP-1 or whether TIMP-1 receptor binding kinetics are altered in painful and non-painful cancers." (PMID 31616247, 2019). "In detail, for those with a CRC pretest probability of 20%, if assessment of TIMP-1 for cancer detection was positive, the posttest probability of having CRC rose to 56%; the probability of having CRC was 9% with a negative TIMP-1 result, which may rule out CRC." (PMID 30458003, 2018). "However, the significant increase of TIMP-1 in TIF did not appear in the plasma of these mice, suggesting utilization, for instance through internalization or enzymatic processing, of this cytokine by cancer or stromal cells." (PMID 27995973, 2016).
infection (91 papers, 2006 to 2025). The state of being infected such as from the introduction of a foreign agent such as serum, vaccine, antigenic substance or organism. "In NEC, elevated intestinal expression of ECM-associated proteins, especially MMP-2, −9 and TIMP-1,−2, facilitates the recruitment of immune cells to cross the endothelial and epithelial layers and reach the infection sites." (PMID 33133078, 2020). "The mRNA levels of MMP-3, MMP-8, MMP-9, and TIMP-1 were analyzed 12 h after FT explant infection with Ngo strain P9, variant 17 (Pil+Opa+)." (PMID 28932707, 2017). "In addition, we observed lower levels of the fibrosis-associated immunopathologic elements MMP-9 and TIMP-1 in the ICOSL KO mice compared to the controls at the advanced stage of infection (16 weeks)." (PMID 25590646, 2015). "The only cytokine that was different between vaccine groups prior to infection was a statistically reduced concentration of the tissue inhibitor of metallopeptidases (TIMP-1) in the vaginal lumen of 4CMenB-vaccinated animals (P = 0.0262)." (PMID 40237483, 2025). "Analysis of pro-tumorigenic markers revealed that 4T1 upregulated expression of epithelial–mesenchymal transition (EMT)-related Fn1 and Timp1 in macrophages, but infection reduced it." (PMID 40547518, 2025). "For instance, we were unable to measure the kinetics of circulating TIMP‐1 in different stages of the infection, which is critical for the potential use of TIMP‐1 as a prognostic biomarker." (PMID 39267201, 2024). "Both MMP-7 and its inhibitor TIMP-1 were upregulated in IAV infected mice: MMP-7 colocalized with IAV, while TIMP-1 was limited to cells adjacent to infection." (PMID 39312544, 2024). "While the CD4+ T cell expression of Timp1 was thought to explain the delayed migration of CD4 compared to CD8+ T cells into the brain parenchyma, infection of Timp1−/− mice surprisingly showed increased CD4+ T cell retention in the perivascular space." (PMID 38140641, 2023). "In our acute infection model, TIMP1 gene was significantly upregulated in alveolar and vascular regions." (PMID 37640792, 2023). "In conclusion, the present study is the first to demonstrate a connection of plasma MMP-8 and MMP-8/TIMP-1 to disease severity, presence of a deep infection focus and mortality in MS-SAB patients." (PMID 34043679, 2021). "At 24 h post infection, these pericytes expressed higher levels of IL-8, TIMP-1 (tissue inhibitor of metalloproteinase-1), and RANTES, but lower levels of MMP9." (PMID 30909422, 2019). "When the ages at the first episode of infection for the multiple-ARTIs group and Log2 transformation were used, two cytokines TIMP-1 (P < 0.001) and PDGF-BB (P = 0.005), as well as age (P = 0.039) were identified with significant predictive values." (PMID 31123265, 2019). "It was also demonstrated that the increased expression of the proteins collagen I and metalloproteinase inhibitor-1 precursor (TIMP-1) after infection with S. japonicum was significantly attenuated in mice infected with AAV8-shNLRP3." (PMID 28808303, 2017). "At 24 hours post infection, pericytes expressed higher levels of IL-8, TIMP-1 (tissue inhibitor of metalloproteinase-1), and RANTES (regulated upon activation normal T cell-expressed and presumably secreted) but lower levels of MMP9." (PMID 25573478, 2015). "Inhibition of MMP activity by melatonin often appears to be due to up-regulation of tissue inhibitors of MMPs (i.e.; TIMP-1), which are known to protect CE barrier function in response to infection and trauma." (PMID 25412440, 2014). "The concentration of TIMP-1 protein peaked at 24 hours after infection (6.8-fold vs. sham infection) and subsequently decreased at 36 hours after infection (4.7-fold vs. sham infection)." (PMID 16749930, 2006). "Furthermore, we found two infection-specific fibroblast populations enriched in Lyz2 (and Tagln) and Timp1, identifying their myofibroblast characteristics." (PMID 38767331, 2024).